TBK1 (TANK binding kinase 1)
Diseases named in the same sentence as TBK1 in open-access papers (continued):
Sharing a sentence is not in itself a finding about the gene and the disease.
autoimmune disease (27 papers, 2018 to 2026). A disorder resulting from loss of function or tissue destruction of an organ or multiple organs, arising from humoral or cellular immune responses of the individual to their own tissue constituents. "Considering the association of IFIT3/TBK1 with autoimmune diseases, we propose a potential relevance of IFIT3/TBK1 in SSc." (PMID 39305055, 2024). "This understanding of TBK1’s molecular role provides valuable insights into the underlying mechanisms of autoimmune diseases, offering potential targets for therapeutic intervention." (PMID 38765007, 2024). "All these results suggest the pathogenic role of TBK1 in autoimmune diseases including RA, thus proposing TBK1 as a potential therapeutic target." (PMID 37935918, 2023). "Our study documents a novel TBK1 inhibitor, which serves as a potential therapeutic target for autoimmune diseases, and elucidated a significant function for MAP4K1 linked to innate immunity in addition to subsequent adaptive immunity." (PMID 34908452, 2021). "TBC1D9 appears to be a specific regulator in response to Ca2+ signaling and could regulate TBK1 activation associated with autoimmune disease." (PMID 35359935, 2022). "Therefore, this study documents a novel TBK1 inhibitor, which serves as a potential therapeutic target for autoimmune diseases, and elucidated a significant function for MAP4K1 linked to innate immunity and subsequent adaptive immunity." (PMID 34908452, 2021). "Although no particular TBK1 genetic variants have to date been directly linked to the development of autoimmune diseases, the diverse functions of TBK1 may contribute to one or more aspects of autoimmunity, which is the focus of this review." (PMID 29559975, 2018). "Therapeutic TBK1 inhibition may therefore lead to premature aging and/or death of pathogenic immune cells, such as long-lived plasma cells, and memory B cells in autoimmune diseases." (PMID 29559975, 2018). "Previous studies have indicated the potential involvement of TBK1 in inflammatory and autoimmune diseases, which can promote activation of the NF-κB and interferon regulatory factor 3 (IRF3) pathways, as well as the M1 polarization of macrophages." (PMID 40746530, 2025). "TBK1 antagonists represent another therapeutic option for the treatment of autoimmune diseases and interferonopathies." (PMID 38953896, 2024). "TBK1 emerges as a pivotal player in autoimmune diseases and the development of inflammatory arthritis resulting from compromised DNA clearance." (PMID 38765007, 2024). "For example, elevated TBK1 expression was commonly observed in autoimmune diseases including systemic lupus erythematosus (SLE), primary Sjögren’s syndrome (pSS) and systemic sclerosis (SSc) patients." (PMID 37935918, 2023). "In contrast, 26 (IC50 = 13 nM), also with an imidazopyridine backbone, was found to be a potent, low toxicity inhibitor of TBK1 with promising therapeutic effects in mice against autoimmune diseases such as systemic lupus erythematosus." (PMID 36172373, 2022). "Growing evidence also revealed the aberrant TBK1 activity in a variety of autoimmune diseases and cancers." (PMID 33411856, 2021). "First, the association between ALS and autoimmune diseases has already been described and recently, TBK1 (TANK-binding kinase 1), a gene involved in inflammatory response and innate immunity, has been linked to the ALS/FTD spectrum." (PMID 33281700, 2020). "However, TBK1/IKKε inhibition by Compound II was shown to ameliorate autoimmune disease phenotypes in the Trex1-/- mouse model for Aicardi–Goutières syndrome, decreasing IFN gene signature and autoantibody titres as well as increasing survival." (PMID 40341181, 2025). "It plays a crucial role in variouscellular processes, including the innate immune response to viruses,cell proliferation, apoptosis, autophagy, and antitumor immunity.Dysregulation of TBK1 activity can lead to autoimmune diseases, neurodegenerativedisorders, and cancer." (PMID 39289178, 2024).
autoimmune disease (continued). "However, overactivation of TBK1 is closely related to dysregulation of immune responses, which is key pathogenesis of autoimmune diseases." (PMID 37935918, 2023). "Therefore, the development of small molecules or small peptides as TBK1 inhibitor provides a prospective strategy for the treatment of RA or even other autoimmune diseases." (PMID 37935918, 2023). "TBK1, also known as NF-κB-activating kinase (NAK) or T2K, which is widely expressed in all tissues, has emerged as a prospective therapeutic target, playing increasingly momentous roles in metabolic diseases, autoimmune diseases, and cancer." (PMID 35587686, 2022). "Given the vital role of TBK1 in innate antiviral immunity, TBK1 inhibitors may play indispensable roles in regulating host antiviral responses and are especially considered as promising therapeutic targets for autoimmune diseases." (PMID 34908452, 2021). "Therefore, TBK1 has been proposed to be a potential target, and its inhibitors may be used in clinical therapy for autoimmune diseases." (PMID 34908452, 2021). "However, the results presented in this work showing that inhibition of TBK1/IKKε leads to massively enhanced IL‐17‐induced signaling in both human and murine cell lines argue against potential therapeutic targeting of TBK1/IKKε kinase activity in treatment of IL‐17 mediated autoimmune diseases." (PMID 32696476, 2020). "Therefore, TBK1 is considered a promising target for preventing autoimmune diseases." (PMID 30769920, 2019). "Because long-lived plasma cells or plasma cells deriving from memory B cells can drive persistent autoimmune disease, abrogation of autophagy through TBK1 inhibition might reduce resistance to autonomous cell aging and death, and diminish pathogenic autoantibody responses." (PMID 29559975, 2018). "Consequently, TBK1 stands out as a pivotal element in the molecular pathway contributing to the inflammatory response in RA, presenting itself as a potential target for therapeutic strategies aimed at modulating immune-related mechanisms in this autoimmune disorder." (PMID 38765007, 2024). "Herein, we focus on the key pathways mediated by cGAS-STING and various cGAS-STING-TBK1 signaling related autoimmune diseases, as well as the recent development of cGAS, STING, or TBK1 selective inhibitors." (PMID 36172373, 2022). "STING has been recognized as an activator of immune responses by TBK1/IRF3 and NF-κB pathways, and it is suggested to play critical roles in host defense, autoimmune diseases, and tumor immunity." (PMID 30595664, 2018). "Notably, TBK1 and PIK3CA have been reported to play key roles in various autoimmune diseases and are potential therapeutic targets." (PMID 37823298, 2024). "Interestingly, treatment with the USP8 inhibitor significantly reduced the protein levels of MDA5 and p‐TBK1 in PBMCs, suggesting that USP8 could be a promising therapeutic target for treating MDA5‐related autoimmune diseases." (PMID 40525588, 2025).
melanoma (27 papers, 2016 to 2026). A malignant, usually aggressive tumor composed of atypical, neoplastic melanocytes. "Accordingly, TBK1 inhibitors have tumor inhibitory effects associated with improved sensitivity to immunotherapy in several cancer types, including melanoma and liver cancer." (PMID 38816352, 2024). "This was supported further by another study that demonstrated that the loss of Tbk1 significantly enhanced the antineoplastic effect of PD-1 blockade in melanomas and in other models of malignancy." (PMID 35395857, 2022). "A growing number of studies have suggested that aberrant activation of TBK1 is closely associated to the occurrence and development of cancer, such as lung, breast, colon, bladder, glioblastoma, melanoma, and pancreas cancers." (PMID 35587686, 2022). "UV exposure significantly reduced the susceptibility of melanoma cells to CD8+ T cell-dependent cytotoxicity through activation of the HMGB1/TBK1/IRF3/NF-κB cascade which in turn triggers the PD-1/PD-L1 checkpoint." (PMID 36012593, 2022). "Several IKKε/TBK1 target genes have already been associated with melanoma initiation and progression." (PMID 32630674, 2020). "One melanoma study focused on cancer resistant to inhibitors of BRAF, a commonly mutated protein in melanoma, and showed that a subset is sensitive to TBK1/IKKε inhibition (compound II, along with other inhibitors)." (PMID 30223576, 2018). "We generated polyclonal functional TBK1 KOs in two different melanoma cell lines (BLM, D10) and observed that loss of TBK1 alone is able to sensitize cells to T cell challenge in some melanoma cell lines, while knocking out both TBK1 and IKKε is required in others." (PMID 41315176, 2025). "Functional knockouts of TBK1 and IKKε in melanoma cells result in heightened sensitivity not only in CD8 T cell but also in Natural Killer cell attacks." (PMID 41315176, 2025). "Further study showed that PSV inhibited the production of IFN-β by cleaving mitochondrial antiviral signaling (MAVS) and degrading melanoma differentiation-associated gene 5 (MDA5) and TANK-binding kinase 1 (TBK1) through viral 3Cpro." (PMID 35782136, 2022). "In primary melanoma patient samples, TBK1 is hyperactive in a subtype of BRAF/MEK inhibitor-resistant tumor cells; this subtype of melanoma displays hyperactive TLR/innate immune system signaling." (PMID 35395857, 2022). "The inhibition of IKKε/TBK1 by the administration of amlexanox reduced the proliferation, migration and invasion potential of melanoma cell lines." (PMID 32630674, 2020). "The proliferation of A375M and SK-Mel-28 human melanoma cells was examined after the incubation of the cells with increasing concentrations of the IKKε/TBK1 small molecule inhibitor amlexanox." (PMID 32630674, 2020). "We showed that IKKε and TBK1 proteins are overexpressed in human melanoma cell lines as well as the metastatic melanoma tissue of patients." (PMID 32630674, 2020). "We assessed IKKε and TBK1 expression in human malignant melanoma cells, primary tumors and the metastasis of melanoma patients." (PMID 32630674, 2020). "In slices of primary human melanoma, we performed a multiplex immunofluorescence analysis and observed the expression of both IKKε and TBK1 in pigmented tumor cells in the melanoma." (PMID 32630674, 2020). "To gain insight into the potential functional relevance of IKKε and TBK1 in melanoma, we assessed the expression levels of IKKε and TBK1 in two different human melanoma cell lines in comparison with melanocytes." (PMID 32630674, 2020). "In this study, we investigated the expression of IKKε and TBK1 in human melanoma cells, as well as in human tissue samples comprising naevi, primary melanoma and melanoma metastasis." (PMID 32630674, 2020). "In these studies, TBK1 inhibition was suggested as a therapeutic option for the treatment of special melanoma specimens." (PMID 32630674, 2020).
melanoma (continued). "TBK1 has already been interconnected with special subsets of melanoma, while the function of IKKε in the initiation and progression of human melanoma is not known so far." (PMID 32630674, 2020). "Melanoma metastasis revealed a significantly higher protein expression of IKKε and TBK1 in comparison to naevi, thus further hinting at a relevant role of IKKε and TBK1 in the pathophysiology of skin cancer." (PMID 32630674, 2020). "Mitogen-activated kinases (MAPKs) constitute further important regulatory genes in IKKε/TBK1-mediated signal transduction which are also constitutively activated in melanoma, thereby controlling the proliferation, survival and invasion of the tumor cells." (PMID 32630674, 2020). "The present study aimed to further elucidate the impact of pharmacological IKKε and TBK1 inhibition in human malignant melanoma." (PMID 32630674, 2020). "Consistent with this overall model, TBK1 was identified (among others) in a CRISPR screen as promoting resistance to immunotherapy in a melanoma tumor model." (PMID 30223576, 2018). "Another AZ derivative AZ13102909 has an IC50 of 0.005 μM against TBK1, promoting apoptosis in melanoma cells." (PMID 30349097, 2018). "Using both thymoma and melanoma models, it has been shown that specific deletion of TBK1 in dendritic cells leads to reduced tumor growth and increased survival." (PMID 30223576, 2018). "Additionally, TBK1/IKKε knockouts of both melanoma cell lines exhibited increased RIPK1 S166 phosphorylation, indicating heightened RIPK1 activation within the TNFR1 complex compared to WT controls." (PMID 41315176, 2025). "In summary, our data indicate that IKKε and TBK1 might contribute to growth and metastasis of malignant melanoma." (PMID 32630674, 2020). "Furthermore, a subset of BRAF/MEK-inhibitor-resistant melanoma cells showed sensitivity towards different IKKε/TBK1 inhibitors." (PMID 32630674, 2020). "Furthermore, we assessed the effect of the selective TBK1/IKKε inhibitor amlexanox on tumor cell growth, migration and invasion in cell culture and in an in vivo melanoma xenograft model in nude mice." (PMID 32630674, 2020). "The impact of TBK1 and IKKε in human malignant melanoma is only scarcely explored." (PMID 32630674, 2020). "Consequently, such melanoma cells are vulnerable to treatment with a TBK1 inhibitor." (PMID 35395857, 2022). "Amlexanox significantly reduced the constitutive phosphorylation of p65 and p42/44 in SK-Mel-28 melanoma cells, indicating that these targets are involved in the anticancerogenous effects of IKKε/TBK1 inhibition, while Akt1 and p38 might only play a minor role in this context." (PMID 32630674, 2020). "After the amlexanox treatment, we detected a significant downregulation of LC3B-II and an upregulation of p62, indicating that the inhibition of TBK1 and/or IKKε counteracts the induction of autophagy and might thereby inhibit the proliferation of melanoma cells." (PMID 32630674, 2020). "It is known that TBK1, but not IKKε, is overexpressed in mutant NRAS melanoma cells and associated with tumor cell proliferation, migration and invasion, which could be ameliorated by the suppression of TBK1." (PMID 32630674, 2020). "Additionally, TBK1 has an oncogenic role in melanoma and non-small cell lung cancer." (PMID 30223576, 2018). "We demonstrated the efficacy of LiSmore in vivo by showing light-triggered TBK1 and IRF3 phosphorylation in LiSmore-engineered bone marrow-derived dendritic cells (BMDCs) within the tumor-draining lymph nodes (tdLNs) of B16 melanoma-bearing mice." (PMID 37673917, 2023). "BAY-985 showed strong inhibition activity on TBK1 (IC50 = 2 nM) and IKKε (IC50 = 2 nM); however, it displayed weak antitumour activity in a xenograft model of SK-MEL-2 human melanoma cell line." (PMID 35587686, 2022).
melanoma (continued). "Increasing or decreasing TBK1 activity by various approaches in many cell types (e.g., MEFs, HEK293 cells, U2OS cells, HeLa cells, MNT1 melanoma cells, or HCT116 colorectal cancer cells) led to correspondingly similar changes in Akt S473 phosphorylation." (PMID 34245780, 2021). "A Western blot analysis revealed a relatively low expression of both IKKε and TBK1 proteins in human HERMES1 melanocytes, which were significantly elevated in A375M and SK-Mel-28 melanoma cells." (PMID 32630674, 2020). "Concurrently, we show that STING is phosphorylated which subsequently leads to the phosphorylation of TBK1 and IRF3 in melanoma cells when treated with diABZI." (PMID 32477956, 2020). "In addition, TBK1 was involved in NF-кB activation and the subsequent upregulation of PD1-L in a model of the UV light-induced activation of melanoma cells." (PMID 32630674, 2020). "SPOP loss consistently increased STING protein levels, but not those of cGAS, TBK1, or IRF3, across human melanoma (A2058, HMCB, and MeWo), mouse melanoma (B16), human RCC (A498, 786-o, and UMRC6), mouse RCC (Renca), and HEK293 cells." (PMID 41148213, 2025). "By measuring the level of STING, TBK1 and IRF3 phosphorylation in pDCs exposed to melanoma supernatants, we could not detect evidence of molecular impairment of the STING pathway." (PMID 38239354, 2023).
Insulin resistance (24 papers, 2013 to 2025). Increased resistance towards insulin, that is, diminished effectiveness of insulin in reducing blood glucose levels. "Surprisingly, adipose TBK1 deficiency exaggerates inflammation and insulin resistance, demonstrating a beneficial role of adipose TBK1 in metabolism." (PMID 34665236, 2021). "The activation of the TBK1-mTORC/IL-17 axis in the adipose tissues of diet-induced obese mice reduces the expression of anti-inflammatory genes in these tissues, attenuating insulin resistance and improving glycemic control in these mice." (PMID 40076567, 2025). "In obese Zucker rats and HFD-fed mice, TBK1 phosphorylates the insulin receptor on Ser994, contributing to insulin resistance." (PMID 39669992, 2024). "Further, we investigated if TBK1 pharmacological inhibition using Amlexanox can rescue the insulin resistance in STK38-overexpressing HepG2 Cells." (PMID 37028764, 2023). "Based on the observations, we propose STK38 increase the expression of some inflammatory cytokines via TBK1 signaling pathways, both of which are involved in the pathogenesis of hepatic as well systemic insulin resistance by interfering with insulin signaling and action." (PMID 37028764, 2023). "This evidence suggests that TBK1 could be involved in in vivo insulin resistance." (PMID 33544228, 2021). "Moreover, a high fat diet can positively modulate TBK1 gene expression in the liver and white adipose tissue whilst its accumulation in lipid rafts of hypothalamic neurons disrupts IR activation as well as AKT signaling, suggesting a potential role of TBK1 in brain insulin resistance." (PMID 31231176, 2019). "Furthermore, TBK1 is involved in insulin receptor signaling and might therefore form a link between inflammation and insulin resistance/diabetes." (PMID 25997745, 2015). "In glucose metabolism, inhibition of the TBK1-mediated NF-κB-MCP1 signaling pathway reduces pro-inflammatory macrophage recruitment and improves insulin resistance, resulting in efficacy in NAFLD mice." (PMID 40076567, 2025). "Reduced STK38 (HFD+shRNA STK38) ameliorates HFD-induced impaired glucose tolerance, insulin resistance, and hepatic steatosis in HFD mice mainly by controlling hypophosphorylation of TBK1." (PMID 37028764, 2023). "In contrast, Amlexanox is not only a non-specific GRK inhibitor but also a dual inhibitor of TBK1/IKKε, which reduces inflammation and inflammation-related insulin resistance, resulting in improved liver steatosis." (PMID 40666930, 2025). "We revealed that liver TBK1 phosphorylation was enhanced in DIO mice and positively correlated with diet-induced local (hepatic and adipose tissue) and systemic metabolic dysregulation and insulin resistance." (PMID 28743914, 2017). "Although pharmacologic inhibition or genetic ablation of IKKβ defined a role for this kinase in insulin resistance, the roles of the noncanonical kinases IKKε and TBK1 are less certain." (PMID 24368730, 2013). "Unlike intrathecal injection of TBK1-siRNA, systemic application of AMX improved insulin resistance in PDN mice; however, it exhibited no significant changes in blood glucose and body weight." (PMID 39030571, 2024).